ACTR3C (actin related protein 3C)
Description:
May play a role in the suppression of metastatic potential in lung adenoma carcinoma cells.
Synonyms: ARP11
Tractability: Antibody: UniProt predicts a signal peptide or a membrane-spanning region. PROTAC: ubiquitination databases record sites on it.
Gene: Protein-coding gene on chromosome 7 (150,243,916 to 150,323,725, reverse strand). Ensembl gene ENSG00000106526.
Gene Ontology:
Cellular component: extracellular exosome
Genetic constraint (gnomAD): Loss-of-function variants: 15 observed, 22.07 expected, observed/expected ratio (o/e) 0.68, 90% interval 0.45 to 1.05. The synonymous counts are far from expectation, so gnomAD's model fits this gene poorly and the ratio says little. Missense variants: 173 observed, 221.51 expected, observed/expected ratio (o/e) 0.78, 90% interval 0.69 to 0.89. Synonymous variants: 50 observed, 81.24 expected, observed/expected ratio (o/e) 0.62, 90% interval 0.49 to 0.78.
Homologues: Orthologues: rat Actr3b (90% identical), mouse Actr3b (90% identical), zebrafish actr3b (83% identical), chimpanzee ACTR3C (65% identical). Paralogues in human: ACTR3B (91% identical), ACTR3 (84% identical), ACTA1 (39% identical), ACTA2 (39% identical), ACTC1 (39% identical), ACTG2 (39% identical), ACTB (38% identical), ACTG1 (38% identical), ACTBL2 (35% identical), ACTR1A (34% identical), ACTR1B (33% identical), ACTR2 (32% identical), and 14 more.
Diseases named in the same sentence as ACTR3C in open-access papers:
ACTR3C is named in the same sentence as 5 diseases in open-access papers, as found by Europe PMC text mining. Sharing a sentence is not in itself a finding about the gene and the disease. The quoted sentences say what the papers report.
chordoma (1 paper, 2022). Chordomas are rare malignant tumors arising from embryonic remnants of the notochord in axial skeleton. "Additionally, BATF, ACTR3C, and FGFBP2 have been implicated in cancers other than chordomas." (PMID 36439461, 2022).
keloid (1 paper, 2022). An irregularly shaped, elevated mark on the skin caused by deposits of excessive amounts of collagen during wound healing. "ACTR3C was found hypermethylated in keloids, and the mRNA expression of ACTR3C was statistically significantly different between keloid and normal skin." (PMID 36439461, 2022).
ACTR3C also shares sentences with these, for which no sentence is quoted: cancer (2 papers); melanoma (1); skin cutaneous melanoma (1).